CXCR4 (C-X-C motif chemokine receptor 4)
Diseases named in the same sentence as CXCR4 in open-access papers (continued):
Sharing a sentence is not in itself a finding about the gene and the disease.
prostate carcinoma (continued). "Although it was previously reported that the sensitivity to DTX was increased in prostate cancer after administration of the CXCR4 antagonist, AMD3100, our study demonstrates for the first time that the CXCR4 inhibition increases antitumor effects of DTX alone in bone microenvironment." (PMID 31877673, 2019). "A very recent paper even reported that CT treatment of prostate cancer stem cells could inhibit their proliferation and tumorigenesis by downregulating the expression of stemness genes including Nanog, SOX2, Oct4, and CXCR4." (PMID 30972427, 2019). "Furthermore, inhibition of GPC-1 decreased several markers of prostate cancer aggression, such as MMP-9, E-Cadherin (E-Cad), N-Cadherin (N-Cad), CXCR4, vimentin (VIM), Zeb1 and Zeb238–40, as determined using qRT-PCR." (PMID 31391540, 2019). "Similar results were obtained with another cell line expressing both uPAR and CXCR4, the prostate carcinoma PC3 cell line (not shown)." (PMID 26082201, 2015). "Thus, androgens have dose-dependent effects on the intracellular localization and co-localization of CXCR4 and CXCR7 proteins in LNCaP prostate-cancer cells." (PMID 25884570, 2015). "In addition, Pim-1 has been shown to regulate the CXCR4/CXCL12 chemokine pathway, which plays an important role in migration and invasion of both leukemic and prostate cancer cells." (PMID 26075720, 2015). "We hypothesize that loss of PTEN and subsequent activation of Akt, frequent occurrences in prostate cancer, regulate the CXCL12/CXCR4 signaling axis in tumor growth and bone metastasis." (PMID 23902739, 2013). "While the role of CXCR4 has been examined in the cancer stem cell context in pancreatic cancer, characterization of CXCR4 signaling in prostate cancer progenitors has not been reported." (PMID 22359577, 2012). "CXCL12 expression was significantly higher in human prostate cancer tissue than hyperplastic prostate tissues, suggesting that CXCL12 has an autocrine regulatory role via its receptor CXCR4 in the regulation of prostate cancer cell migration, invasion, and metastasis." (PMID 22074556, 2011). "We demonstrated that forced expression of SLUG elevated CXCR4 and CXCL12 expression in human prostate cancer cell lines PC3, DU145, 22RV1, and LNCaP; conversely, reduced expression of SLUG by shRNA downregulated CXCR4 and CXCL12 expression at RNA and protein levels in prostate cancer cells." (PMID 22074556, 2011). "Thus, our new findings that CXCL12/CXCR4 is a mediator of SLUG-induced migration and invasion of prostate cancer cells provide insight into the molecular mechanisms by which SLUG promotes tumor cell metastasis in vivo." (PMID 22074556, 2011). "It has been reported that CXCR4 is expressed in prostate cancer cells but not in immortalized prostate epithelial cells." (PMID 22074556, 2011). "To determine whether CXCL12/CXCR4 axis plays a role in SLUG-mediated migration and invasion of prostate cancer cells in vitro, we first tested if forced expression of SLUG increases CXCL12 expression." (PMID 22074556, 2011). "Furthermore, we found that CXCR4, CCL20 and CCR6 are over- and coexpressed in human prostate cancer specimens." (PMID 19340288, 2009). "Prostate cancers, and perhaps other neoplasms, may rely upon the SDF-1/CXCR4 pathway to spread to bone." (PMID 19508713, 2009). "First, because CXCL12 up regulates CD164 expression and stimulates prostate cancer cell proliferation and adhesion, therapies designed to disrupt CD164 or the CXCL12/CXCR4 axis could be used to alter tumor progression via several mechanisms." (PMID 16859559, 2006). "Finally, CTCE-9908 is a CXCL12 analog that strongly blocks the CXCR4/CXCL12 axis, leading to reduced tumor growth and metastases in various preclinical models including osteosarcoma and melanoma, esophageal cancer, breast and prostate cancer." (PMID 40307933, 2025).
prostate carcinoma (continued). "The CXCL12 and chemokine receptors, CXCR4 and CXCR7, are the key factors that link cancer cells and their microenvironment, thus playing a crucial role in tumor initiation and progression, including the migration of prostate cancer cell lines such as PC3 and LNCaP." (PMID 37050202, 2023). "Furthermore, ablation of BACH1 in human colon carcinoma or in prostate cancer cells prevents cell growth, migration, and invasion in vitro, decreasing the expression of its main metastasis-related genes, MMP1, let-7a, and CXCR4." (PMID 32132179, 2020). "Indeed, by knocking down PHF19L, we observed significant induction of multiple genes known to promote changes in cytoskeleton and adhesion, extracellular matrix remodeling, invasion, and metastasis in prostate cancer (including SOX9, SOX4, MMP1, PLAU, EPCAM, CXCR4, LOX, and MET)." (PMID 32155117, 2020). "Therefore, treat prostate cancer cells with AMD3100, a CXCR4 antagonist, may effectively inhibit prostate cancer cell metastasis to bone." (PMID 31753020, 2019). "Our research demonstrated that the expression of CXCL12, CXCR4, MMP-2, and MMP-9 in prostate cancer was much higher than in hyperplastic prostate tissue, implying that these proteins interact with each other and together may regulate chemotactic ability and invasiveness of tumor cells." (PMID 18983683, 2008). "In order to test whether Cxcr4 signaling inhibition in the microenvironment could affect the metastatic cascade in other tumor types, we engrafted another triple negative breast cancer cell line MDA-MB-157, as well as prostate cancer cells PC3-M-Pro4-Luc2 and the Ewing sarcoma cell line WE68." (PMID 30787324, 2019). "Taken together, these studies suggest that targeting the CXCR4/CXCL12 pathway results in decreased prostate progenitor survival in vitro and in vivo in androgen refractory cancer cell lines and potentially could be of therapeutic value against advanced prostate cancers." (PMID 22359577, 2012). "It has been previously proposed that SDF-1α/CXCR4 signalling played role in AT-MSC homing within the sites of tumor formation and recently published data have demonstrated that inhibition of this axis by small molecule inhibitor AMD3100 could abrogate their migration towards prostate cancer cells." (PMID 20509882, 2010). "While only CD117 was a prostate cancer marker in our study, this does not mean that the other markers (CD133, CXCR4 and CD34) were not altered by tumor presence." (PMID 25595903, 2015). "A similar hypoxia-dependent effect on CXCR4, VEGF and PLOD2 induction was observed in response to suppressed Rb expression in LNCaP prostate cancer cells suggesting that this observation is not cell type specific." (PMID 24919196, 2014).
pancreatic cancer (266 papers, 2006 to 2026). "Using an engineered protein to dissect pharmacological signaling of CXCR4 we have extended our initial discovery of partial agonism in pancreas cancer cells to a high-risk hematologic malignancy to examine how agonists of the same receptor function." (PMID 39253415, 2025). "Western blot analysis of the expression of EMT-associated proteins and HIF-1α/SDF-1/CXCR4 of pancreatic cancer tissues revealed that bufalin significantly downregulated vimentin but upregulated E-cadherin in PANC-1 cells." (PMID 32362830, 2020). "CXCL12 interaction with its receptor, CXCR4, causes intracellular actin polymerization, which is necessary for pancreatic cancer cell migration and invasion." (PMID 32292657, 2020). "β-Catenin and CXCR4 have also been implicated in pancreatic cancer progression and metastasis and CXCR4 expression has been correlated with poor survival in PDAC patients." (PMID 28881737, 2017). "In pancreatic cancer the CXCR4-SDF-1α survival axis is associated with the pancreatic cancer drug resistance." (PMID 25821841, 2015). "Our data also suggest that the CXCL12/CXCR4 axis is associated with the formation of lymphatic vessels and blood vessels induced by pancreatic cancer cells." (PMID 23181100, 2012). "Data from in vitro and murine in vivo tumour models underline the critical role of CXCR4/CXCL12 receptor ligand system for pancreatic tumour cells." (PMID 19352387, 2009). "The aim of this study was to determine the role of CXCR4 in pancreatic cancers and elucidate the underlying mechanism." (PMID 19002187, 2008). "The downregulation of CXCR4 might also enhance the infiltration of DP T cells into tumor-rich areas, because pancreatic cancer–associated fibroblasts can retain T cells in the tumor stroma through the CXCR4-CXCL12 axis." (PMID 38335302, 2024). "C-X-C chemokine receptor 4 (CXCR4) expression on tumor cells has been associated with an unfavorable progression and metastasis in cancers including melanoma, ovarian cancer, breast cancer, pancreatic cancer, and prostate cancer." (PMID 35145271, 2022). "Indeed, recently in pancreatic cancer, the CXCR4/CXCL12 axis has been linked to the resistance to immune checkpoint therapy." (PMID 29222645, 2018). "The CXCR4-SDF-1α signaling axis has been implicated in pancreatic cancer drug resistance." (PMID 25821841, 2015). "However, in pancreatic cancer the CXCL12/CXCR4 axis has been functionally implicated in tumor progression by initiating tumor cell migration, invasion, angiogenesis, and putatively inducing metastasis." (PMID 26091099, 2015). "Accordingly, the chemoattracting effect of CXCL12 on CXCR4+ pancreatic cancer cells might reflect a major cause for the formation of metastases directly where CXCL12 is highly expressed such as in lymph nodes, in the liver, lungs, and bone marrow." (PMID 26091099, 2015). "Also a subpopulation of CXCR4 (a receptor for SDF-1α) positive pancreatic cancer cells has been implicated in tumor growth." (PMID 25821841, 2015). "However, the relative mechanism underlying the downstream modulation function of SDF-1/CXCR4 on pancreatic cancer progression is poorly understood." (PMID 19002187, 2008). "Moreover, we defined the CXCR4 over-expressed CTCs subpopulations as HM-CTCs, which could identify high-risk pancreatic cancer subpopulation who were prone to suffering early recurrence and metastasis." (PMID 38983932, 2024). "In addition, in order to investigate the role of CXCR4 in the progression of pancreatic cancer, the present study also analyzed the association between the expression profiles of CXCR4 and clinicopathological factors only in tumor tissues from 33 patients with PDAC." (PMID 37697316, 2023). "The CXCRL12/CXCR4 axis has been implicated in all stages of pancreatic cancer development and contributes to survival, metastasis, chemoresistance and the highly atypical pancreatic cancer microenvironment, which makes this disease particularly difficult to treat." (PMID 33917882, 2021).
pancreatic cancer (continued). "For instance, the CXCR4 antagonist BL-8040 has shown encouraging activity when combined with pembrolizumab and chemotherapy in pancreatic cancer, while balixafortide demonstrated synergistic efficacy with eribulin in metastatic breast cancer." (PMID 40481962, 2025). "Clinical studies for pancreatic cancer targeting CD44 or CXCR4 have encountered toxicity, suboptimal target engagement, or inadequate penetration into thick stromal environments." (PMID 41439922, 2025). "In pancreatic cancer, inhibiting CXCR4 has been shown to enhance T cell infiltration into tumours and synergise with anti‐PD‐1 therapies." (PMID 40292733, 2025). "More recently, a dendrimer nano-radio-vehicle, containing lutetium-177 and encapsulated KRAS membrane association blocking molecule C19, was developed for a dual-targeted radio and chemotherapy in CXCR4+ pancreatic cancer cells." (PMID 40307933, 2025). "This increase in CXCR4 by pancreatic cancer cells, leading to increased CXCL12 production by CAFs, has also been documented by others." (PMID 38339310, 2024). "We found that CXCR4 expression levels were higher in pancreatic cancer cell lines AsPC-1, PANC-1, MIA PaCa-2, BxPC-3, T3M4, and Capan-1." (PMID 38983932, 2024). "In contrast, the CXCL12/CXCR4 axis is involved in the retention of T cells in the tumor stroma of pancreatic cancer." (PMID 38335302, 2024). "In order to further clarify the role of CXCR4 in pancreatic cancer, in vitro and in vivo experiments were performed to clarify the effect of CXCR4 on the metastatic ability of pancreatic cancer cells." (PMID 38983932, 2024). "To further clarify the function of CXCR4 in pancreatic cancer, we established the OE-CXCR4/AsPC-1 cell line to stably over-express CXCR4 in AsPC-1 cells." (PMID 38983932, 2024). "In the COMBAT trial, treatment of pancreatic tumors with a C-X-C motif chemokine receptor 4 (CXCR4) antagonist decreased infiltration of MDSCs and was synergistic with immune checkpoint blockade in pancreatic cancer." (PMID 38474232, 2024). "In pancreatic cancer cell-derived exosomes, proteins CXCR4 (C-X-C motif chemokine receptor 4) and MMP-9 were found to enhance the metastatic capabilities of pancreatic cancer cells." (PMID 38200509, 2024). "For example, when CXCR4 was knocked down, the invasion potential of pancreatic cancer cells in vitro was decreased." (PMID 38835055, 2024). "Effectiveness was measured with analysis of overall survival, disease-free survival, distant recurrence, locoregional recurrence, and measuring of pancreatic cancer stem cells (EpCAM+CXCR4+CD133+)." (PMID 38730669, 2024). "We further verified the function of CXCR4 in promoting the liver metastasis of pancreatic cancer, which was consistent with previous research." (PMID 38983932, 2024). "A specific subpopulation of CSCs, identified by CD133 and CXCR4 markers, is crucial for tumor metastasis in human pancreatic cancer." (PMID 38835055, 2024). "Another study on pancreatic cancer showed that radiation stimulates CAFs to secrete high concentrations of CXCL12 and act on pancreatic cancer cells through CXCR4, directly promoting EMT and tumor cell invasion." (PMID 37607935, 2023). "The inhibition of CXCR4-mediated migration in breast, thyroid, and pancreatic cancer cells by LPA implies that LPA can exert a negative regulatory effect on CXCR4 function in cancer and inflammatory conditions where LPA is abundtant." (PMID 37749552, 2023). "Recently, a nanobody molecule with bi-targeting on PD-L1 and CXCR4 were investigated in a pancreatic cancer since both of the targets are overexpressed in different cancers and play important roles in tumorigenesis." (PMID 38067344, 2023). "There are numerous series of data correlating CXCR4 overexpression with poor prognosis in pancreatic cancer." (PMID 37697316, 2023). "In a human pancreatic cancer xenograft model, the anti-PD-L1/CXCR4 nanobody presented the most effective inhibition on tumor growth." (PMID 38067344, 2023).
pancreatic cancer (continued). "Two interesting matrix remodeling genes are MMP2 and CXCR4, which are involved in promoting cell motility and invasion in pancreatic cancer." (PMID 36765586, 2023). "We have recently observed that CB receptors, as well as HER2 and CXCR4, are overexpressed in pancreatic cancer cell lines, especially in a subset of cancer tumorspheres enriched in chemo-resistant cancer stem cells." (PMID 35204820, 2022). "RAN promotes metastasis and invasion in pancreatic cancer by deregulating the expression of AR and CXCR4." (PMID 35626021, 2022). "Macrophages of these different origins appear to be distinguished by C-X-C motif chemokine receptor 4 (CXCR4) in human pancreatic cancer, where CXCR4-positive macrophages appear to be tissue-resident and have a pro-fibrotic effect." (PMID 36726981, 2022). "The relative expression levels of PD-L1 and CXCR4 on the surface of human pancreatic cancer cell lines (AsPC-1 and Panc-1) were first evaluated." (PMID 36284271, 2022). "A previous study reported that the CXCR4 pathway influences EMT in in vitro models comprising pancreatic cancer cells, and increasing evidence has revealed that tumor metastasis is related to EMT." (PMID 35681259, 2022). "For further experiments after the chemical improvement of the radiotracers, we will establish cell lines with high expression of CXCR4 and integrin αvβ3 by stable transfection to better evaluate the performance of the tracers for pancreatic cancer imaging." (PMID 36145541, 2022). "Among these, the double positivity for CD133 and CXCR4 was suggested to be able to identify a population of pancreatic CSCs that sustains pancreatic tumor growth and is essential for metastasis." (PMID 36142575, 2022). "Further evidence for the role of CXCL12 in T-cell infiltration came from other preclinical studies, where inhibition of CXCR4 (the receptor for CXCL12) enhanced the response to checkpoint inhibition in a pancreatic cancer model." (PMID 35814453, 2022). "For example, CXCL12/CXCR4 axis advanced the invasion and metastasis of pancreatic cancer through complex crosstalk with other pathways, and was correlated with the poor prognosis of patients." (PMID 36419891, 2022). "BL-8040, a small molecule inhibitor of CXCR4 has been shown to expand the benefits of chemotherapy in combination with pembrolizumab on pancreatic cancer." (PMID 36284271, 2022). "It is also noteworthy that several current clinical trials (NCT04177810, NCT02907099) in pancreatic cancer include anti-PD-1/PD-L1 therapies in conjunction to anti-CXCR4 therapies." (PMID 36612166, 2022). "In an immunohistological analysis of 103 patients with pancreatic cancer, strong CXCR4 expression was significantly correlated with advanced pancreatic cancer and reveals a trend for hematogenous metastasis." (PMID 35145271, 2022). "CAFs are also the primary source of CXCL12, which interacts with the receptor CXCR4 to stimulate pancreatic cancer cell proliferation, regulating the infiltration of CTLs and the recruitment of Tregs." (PMID 36284271, 2022). "It is also reported that SDF-1α/CXCR4 signaling can activate β-catenin in colorectal and pancreatic cancer cells 20,21." (PMID 34976212, 2022). "We designed a novel bispecific nanobody (BsNb PX4) targeting PD-L1 and CXCR4, which are involved in the metastasis and progression of pancreatic cancer." (PMID 36284271, 2022). "Accordingly, the expression of CXCR4 mediated the development of liver and lung metastasis in the pancreatic cancer animal model." (PMID 35216235, 2022). "An active phase IIb trial is currently testing the efficacy of the CXCR4 antagonist BL-8040 in combination with pembrolizumab, in patients with pancreatic cancer (NCT02907099)." (PMID 34440844, 2021). "Other reports demonstrated that CQ exerts anti-CSC activity to CSC pancreatic cancer by inhibiting the CXCL12/CXCR4 signaling, resulting in reduced phosphorylation of ERK and STAT3." (PMID 34884848, 2021).